BACE2 (beta-secretase 2)
Diseases named in the same sentence as BACE2 in open-access papers (continued):
Sharing a sentence is not in itself a finding about the gene and the disease.
aging (1 paper, 2021). A developmental process that is a deterioration and loss of function over time. "For example, the microglia AD genes, including APP, CLU, BACE2, and BIN1, are specifically enriched for other diseases such as neurofibrillary degeneration, Parkinson’s dementia, and aging memory impairment." (PMID 34044854, 2021).
autism spectrum disorder (1 paper, 2016). A spectrum of developmental disorders that includes autism, and Asperger syndrome. "In this context, we previously reported that up-regulation of the Autism Spectrum Disorder-associated gene CADPS2, and other neurodevelopmental disorder-related genes (BACE2 and DSCR5) were detected in GS macaques." (PMID 27801835, 2016).
Blindness (1 paper, 2022). Blindness is the condition of lacking visual perception defined as a profound reduction in visual perception. "The specificity of VHH‐B9 for BACE1 also avoids issues of impaired glucose homeostasis, hypopigmentation, seizures, and blindness (among others), which are associated with cross‐reactivity with BACE2, Cathepsin D, and Cathepsin E." (PMID 35352880, 2022).
cardiac arrhythmia (1 paper, 2019). Any disturbances of the normal rhythmic beating of the heart or MYOCARDIAL CONTRACTION. "Aside from BACE2 inhibition, the only other significant off-target (non-BACE1) activity of verubecestat is the inhibition of the hERG channel which is a common cause of QTC prolongation and cardiac arrhythmias." (PMID 31387606, 2019).
colon adenocarcinoma (1 paper, 2021). "Four years later, another study by Tsuji and colleagues, reported the upregulation of BACE2 in colon adenocarcinoma compared to normal tissue." (PMID 33926496, 2021).
colon tumors (1 paper, 2021). "Besides, compared with normal tissue, BACE2 was also observed to be over-expressed in breast and colon tumors." (PMID 33653351, 2021).
colorectal adenoma (1 paper, 2020). An adenoma that arises from the colon or rectum. "In addition, BACE2 expression is also increased in colorectal adenomas." (PMID 31856384, 2020).
cutaneous melanoma (1 paper, 2021). A primary melanoma arising from atypical melanocytes in the skin. "Significantly, both pancreatic adenocarcinoma and cutaneous melanoma expressed elevated levels of APP and BACE2 compared to matched normal tissue." (PMID 33514748, 2021).
Hyperglycemia (1 paper, 2016). An increased concentration of glucose in the blood. "Our findings are consistent with those presented as an abstract by researchers at Novartis; the potent non-selective BACE1/BACE2 inhibitor, SMI NB-360, did not improve hyperglycemia, glucose tolerance or increase beta-cell mass after chronic treatment in diabetic ob/ob mice." (PMID 26840340, 2016).
hyperphosphatemia (1 paper, 2025). Abnormally high level of phosphate in the blood. "Having known that sVEGFR3 shows a fast and sensitive response to BACE2 activity, we uncovered a significant upregulation of BACE2 in LECs with hyperphosphatemia." (PMID 40884245, 2025). "By creating LEC‐specific BACE2 knockout mice or using BACE2 inhibitors, we observed that the lymphatic network was largely recovered in AVFs with hyperphosphatemia." (PMID 40884245, 2025). "Particularly, in mouse AVFs with hyperphosphatemia, we found that BACE2 inhibition could rectify the sVEGFR3‐related VEGF‐C unresponsiveness in LECs, and normalized the lymphatic network to alleviate local inflammation and neointima formation." (PMID 40884245, 2025). "By applying BACE2 inhibitors in the anastomosis area, we rectified the defective lymphatic network and alleviated the local inflammation in mouse AVFs with 5/6 nephrectomy, implicating a therapeutic immunoregulation strategy for AVFs with hyperphosphatemia." (PMID 40884245, 2025). "Considering that overt hyperphosphatemia always inevitably occurs during late CKD progression, inhibiting BACE2 may become one of the promising therapeutic strategies." (PMID 40884245, 2025).
insulinoma (1 paper, 2024). "sVEGFR3 was also detected by immunoblot and MSD-immunoassay in the conditioned medium of Vegfr3-transfected mouse insulinoma MIN6 cells, which express Bace2 endogenously." (PMID 38888964, 2024).
liver fibrosis (1 paper, 2024). "Additionally, BACE2 expression is enhanced in MASH tissues, particularly in those with severe fibrosis, as recently reported for the pediatric population with liver fibrosis." (PMID 39201455, 2024).
lymphedema (1 paper, 2024). Excess fluid collection in tissues, causing swelling. "This raises the possibility of considering therapeutic BACE2 inhibition for conditions with reduced VEGFR3 signaling, such as Milroy disease, which presents with lymphedema and can be caused by a heterozygous loss of VEGFR3 function." (PMID 38888964, 2024).
mental disorder (1 paper, 2022). A disease that has its basis in the disruption of mental process. "Eight genes are implicated in viral (SEC14L1, JMJD6, SRSF2, TMPRSS2, MX1, MX2) or bacterial (COL8A1, SPIRE1) infections, seven genes (MFSD11, METTL23, CTTNBP2, BACE2, IMPA2, MPPE1 and GNAL) are involved in mental disorders and one gene (MGAT5B) is related to the Golgi complex." (PMID 35581286, 2022).
mild cognitive impairment (1 paper, 2019). "In addition, in ε4 non-carriers diagnosed with AD or mild cognitive impairment (MCI), SNPs within the BACE2 locus are associated with cerebrospinal fluid (CSF) levels of Aβ1-42." (PMID 31270419, 2019).
pancreatitis (1 paper, 2015). Inflammation of the pancreas. "During caerulein pancreatitis Bace2 mRNA expression was significantly reduced in both C57BL/6 and Bace1-/- mice as compared to wild-type C57BL/6 mice of the saline group." (PMID 25961820, 2015). "We discuss the results in the context of the applied caerulein induced edematous pancreatitis model and possible compensatory mechanisms via Bace2 that might be responsible for the observed results." (PMID 25961820, 2015).
Parkinson disease (1 paper, 2020). A progressive degenerative disorder of the central nervous system characterized by loss of dopamine producing neurons in the substantia nigra and the presence of Lewy bodies in the substantia nigra and locus coeruleus. "The predisposition genes potentially linked to the neurological form of CD were identified by messenger-RNA (mRNA) profiling: CADPS2 (ASD), CAPN13 (AD), BACE2 (AD, DS), DSCR5 (DS), and PINK1 (Parkinson’s Disease (PD)." (PMID 32751379, 2020).
ulcerative colitis (1 paper, 2024). An inflammatory bowel disease involving the mucosal surface of the large intestine and rectum. "The activity of IL-1R2, linked to ulcerative colitis, is influenced by the BACE2 gene." (PMID 38962743, 2024).
cancer (13 papers, 2020 to 2026). A tumor composed of atypical neoplastic, often pleomorphic cells that invade other tissues. "The mechanisms by which BACE2 activity affects cancer growth seem to be deeply linked to the ability of this protease to process amyloidogenic proteins that in turn modulate TME." (PMID 33926496, 2021). "The KEGG analysis indicated that BACE2 was mainly enriched in processes associated with focal adhesion, cancer‐related pathways and regulation of the actin cytoskeleton." (PMID 31856384, 2020). "Some cancer drivers displayed both decreased accessibility and decreased mRNA levels, e.g., Brca1, E2f7 and Myh11, while others displayed increased accessibility and associated mRNA upregulation, e.g., Msi2, Bace2." (PMID 35269430, 2022). "METHODS: We employed a multi-omics approach, including global and spatial proteomics, lipidomics and N-terminomics, combined with advanced imaging and functional assays to dissect BACE2’s role in lipid regulation and cancer metabolism." (PMID 41507981, 2026). "CONCLUSIONS: Our findings uncover a novel function of BACE2 as a pivotal regulator of lipid transporter shedding, lipid uptake, and LDs homeostasis, ultimately shaping cancer cell metabolic adaptation and proliferation." (PMID 41507981, 2026). "These insights position BACE2 as a promising therapeutic target in lipid-addicted tumors, offering new avenues for cancer treatment." (PMID 41507981, 2026). "In lipid-rich cancer cells this leads to lipolysis and metabolic stress, indicating that BACE2 activity is crucial for preventing lipolysis-induced damage." (PMID 41507981, 2026). "RESULTS: Analysis of patient tumor biopsies and cancer cell lines demonstrated a strong positive correlation between BACE2 expression, lipid metabolism, and lipid droplets (LDs) accumulation." (PMID 41507981, 2026). "In this study, we identify Beta-secretase 2 (BACE2), a sheddase overexpressed in several solid tumors, as a critical regulator of lipid metabolism, revealing novel pathways underlying cancer metabolic vulnerability." (PMID 41507981, 2026). "The PRDM family members play role in cancer suppression, while ABCG1, BACE2, and TFF1 are implicated in tumor formation in various studies." (PMID 38395755, 2024). "Some of the prominent genes we identified through the networks are DOK5, APP, CTNND1, STX6, STX10, STX16, BACE1, and BACE2; which, agree with the regulation of various cancers based on their co-expression patterns in GeneMANIA." (PMID 37218885, 2023). "It has to be noted however, that the overexpression of BACE2 in cancer tissues seems to be quite widespread justifying further studies to discover other pathways implicated in the development and progression of the disease." (PMID 33926496, 2021). "Both studies describe an upregulation of BACE2 in an aggressive and advanced stage building a correlative link between BACE2 and cancer progression." (PMID 33926496, 2021). "Gene Ontology (GO) analysis revealed that the genes that were positively related to BACE2 were mainly involved in cancer‐promoting processes, including cell adhesion, cell proliferation, cell migration and extracellular matrix disassembly." (PMID 31856384, 2020). "BACE2 is a β-secretase protein that is overexpressed in cancers." (PMID 39981249, 2025). "Indeed, even if BACE2 seems to be the β-secretase mainly involved in cancer, the availability of BACE2 specific inhibitors is problematic due to the high grade of homology with BACE1." (PMID 33926496, 2021). "As expected, BACE1 expression does not correlate with the prognosis of the disease pointing out that BACE2, and not BACE1, seems to be mainly involved, directly or through its targets, in the pathogenesis and/or progression of cancer." (PMID 33926496, 2021).
tumor (12 papers, 2020 to 2026). "Finally, functional experiments elucidated the causal relationship between BACE2-dependent lipid regulation and tumor cells proliferation." (PMID 41507981, 2026). "Indeed, BACE2 is highly expressed in a broad range of tumor tissues and its expression is associated with worse prognosis." (PMID 33926496, 2021). "Inhibition of fatty acid uptake via CD36 blockade or suppression of ATGL-mediated lipolysis restores LDs integrity and rescues cell viability, underscoring BACE2’s role in maintaining a balanced lipid state critical for tumor cell survival and proliferation." (PMID 41507981, 2026). "BACE2 increases tumor growth by hyperactivating the NF-κB pathway via a series of phosphorylation cascades of different members of this pathway." (PMID 35884586, 2022). "Bioluminescence imaging 7 days after GSC implantation as well as the survival data demonstrated that BACE2 knockdown inhibited tumor growth compared with that in the shNT group, and radiotherapy was administered at this time." (PMID 33413577, 2021). "Recently, the BACE2 processing of amyloidogenic proteins, has also been suggested to affect tumor proliferation in a cell autonomous fashion." (PMID 33926496, 2021). "We found that BACE2 knockdown led to significantly decreased levels of p‐p65 and key tumour promoters, namely CDK2, CDK4, cyclin D1 and c‐Myc." (PMID 31856384, 2020). "BACE2 knockdown suppressed cell invasion, cell migration and tumour growth both in vitro and in vivo, while BACE2 overexpression promoted the mesenchymal transition and cell proliferation." (PMID 31856384, 2020). "Moreover, BACE2 can affect intracellular pathways enhancing tumor proliferation via the upregulation of the NFkB pathway or through Ca2+ intracellular accumulation." (PMID 33926496, 2021). "Finally, GSEA revealed that high BACE2 expression was statistically associated with epithelial–mesenchymal transition (EMT), tumour invasion, tumour metastasis and the regulation of the G1‐S phase transition in the cell cycle." (PMID 31856384, 2020). "Very little was found in the literature on the relationship between BACE2 expression and tumours." (PMID 31856384, 2020). "For instance, BACE2 is highly expressed in breast and colon tumours compared with normal tissues." (PMID 31856384, 2020). "In this disease, BACE2 has been linked to an increased expression of TMEM38B (Trimeric intracellular cation channel 38b), a calcium channel, leading to Ca2+ intracellular accumulation and activation of the PI3K (Phosphoinositide 3-kinase) pathway that sustain tumor proliferation." (PMID 33926496, 2021). "Notably, according to the GO analysis and GSEA, BACE2 might indeed promote tumour cell proliferation through regulation of the cell cycle." (PMID 31856384, 2020). "However, the function and potential mechanism of BACE2 require investigation in these tumours." (PMID 31856384, 2020). "In addition, BACE2 also downregulated MMP2, which plays a significant role in type IV collagen degradation during tumour invasion and migration." (PMID 31856384, 2020).
infection (5 papers, 2017 to 2022). The state of being infected such as from the introduction of a foreign agent such as serum, vaccine, antigenic substance or organism. "In this study, we evaluated the interaction between the SARS-CoV-2 RBD and intermediate horseshoe bat ACE2 (bACE2-Ra), and investigated the infection efficiency of pseudotyped SARS-CoV-2 via bACE2-Ra." (PMID 35874946, 2022). "Here, we report that SARS-CoV-2 RBD can bind to bACE2-Rm with substantially lower affinity than that to hACE2, and infection of host cells carrying bACE2-Rm was also investigated with pseudotyped or wild SARS-CoV-2." (PMID 33335073, 2021). "The binding affinity between SARS-CoV-2 RBD and bACE2-Rm is substantially lower than that between SARS-CoV-2 RBD and hACE2, which is also supported by the lower infection efficacy with pseudotyped SARS-CoV-2." (PMID 33335073, 2021). "Inhibition of the common shedding proteases BACE1 and BACE2, which are expressed in A549 cells, with the drug C3 did not alter GFP expression, ruling out an involvement of both proteases in SARS‐CoV‐2 spread in this infection model." (PMID 35527514, 2022). "Infection of the SARS-CoV-2 to HeLa cells expressing monkey ACE2 or bACE2-Rm could be detected after 48 h of incubation, while no SARS-CoV-2 could be detected in HeLa cells without ACE2 receptor expression." (PMID 33335073, 2021).
neurodegenerative disease (5 papers, 2014 to 2025). A disorder of the central nervous system characterized by gradual and progressive loss of neural tissue and neurologic function. "Lastly, in cases where the present study evidenced down-regulated expression at the protein level (CDH4, MSN, BACE2) the next steps could involve the investigation of murine knock-outs against the background of neurodegenerative disease phenotypes." (PMID 28798667, 2017).
neurological disorders (1 paper, 2022). "Indeed, identified genes are implicated in viral (SEC14L1, JMJD6, SRSF2, TMPRSS2, MX1, MX2) bacterial (COL8A1, SPIRE1), and neurological disorders (MFSD11, METTL23, CTTNBP2, BACE2, IMPA2, MPPE1 and GNAL), or in the functions of the Golgi complex (MGAT5B), organelle where viral envelope is occurred." (PMID 35581286, 2022).
BACE2 also shares sentences with these, for which no sentence is quoted: polycystic kidney disease (2 papers); acute pancreatitis (1); bladder cancer (1); cerebral amyloid angiopathy (1); cervical cancer (1); co-infection (1); colon (1); colorectal cancer (1); gastric cancer (1); hepatocellular carcinoma (1); Hyperinsulinemia (1); juvenile neuronal ceroid lipofuscinosis (1); lung carcinoma (1); malaria (1); memory impairment (1); metabolic disorder (1); Milroy disease (1); neurodevelopmental disorder (1); pancreatic adenocarcinoma (1); prostate carcinoma (1); renal carcinoma (1); Stroke (1); systemic sclerosis (1); T-cell lymphoma (1).